INS (insulin)
Diseases named in the same sentence as INS in open-access papers (continued):
Sharing a sentence is not in itself a finding about the gene and the disease.
cancer (continued). "Additionally, the insulin and IGF-1 levels in cancer patients are proportional to cancer-related mortality." (PMID 25866823, 2015). "The insulin/IGF system also contributes to CRC resistance to both conventional and targeted anti-cancer agents, leading to increased PI3K/Akt signaling that hinders the apoptotic signals triggered by chemotherapeutic drugs and desensitizes CRC cells to the effect of anti-EGFR antibodies." (PMID 26528439, 2015). "In exploring the role of the IGF-II/IR-A signaling pathway in promoting cancer cell proliferation, survival, and migration, Belfiore and colleagues demonstrated that IGF-II promotes a signaling pattern that differs from insulin while also sharing some common signaling pathways." (PMID 26217307, 2015). "However, in order to understand the links between dysregulated insulin/IGF signaling and cancer as well as the variety of ideas regarding how to most effectively block this signaling, one must first appreciate the system’s complexity." (PMID 26029167, 2015). "However, all three types of receptor dimers can react with both insulin and IGF1, albeit with variable affinity, making it difficult to establish which ligand plays the main role in cancer." (PMID 26284118, 2015). "Moreover, it has been well documented that direct or indirect inhibition of insulin (or IGF-1)/PI3K/Akt/mTOR pathway, such as rapamycin, metformin and dietary protein restriction, have cancer- preventing or treating effects." (PMID 24970814, 2014). "Furthermore, the insulin and IGF-1 receptors form heterodimers that bind IGF-2, another ligand of the IGF family produced by cancer cells." (PMID 25295009, 2014). "We now find that XMetS, a positive allosteric modulator of the INSR, also does not agonize or potentiate insulin-mediated cancer cell proliferation." (PMID 24533136, 2014). "Accordingly, insulin-independent, DR-refractory MCF10DCIS.com xenotumors were exquisitely sensitive to the daily, i.p. administration of 200 mg kg−1 metformin beginning 1 week before the inoculation of cancer cells." (PMID 24909934, 2014). "We applied strict and innovative criteria to obtain new users of glargine and NPH without prevalent cancer during 19 months prior to insulin initiation." (PMID 25329887, 2014). "The phenomenon of improvement in cancer outcome appears specific to metformin and is not seen with insulin or sulfonylureas." (PMID 24879130, 2014). "In order to investigate this relationship, we prospectively categorized cumulative insulin dose and found that adjustment of insulin dose did not change the neutral effect of glargine insulin on the incidence of cancer." (PMID 25329887, 2014). "The fact that these diseases are regarded as risk factors for cancer raises the question whether there is a direct connection between insulin and INSR and cancer." (PMID 24434591, 2014). "Our study thus adds to the evidence that insulin glargine does not increase the risk for any cancer outcomes when compared with its main treatment alternative, NPH insulin." (PMID 25329887, 2014). "Since both IR-A and IR-B are regulated by insulin, IGF1 and IGF2 through autocrine and/or paracrine mechanisms, the microenvironment of the cancer site may also contribute to the relationship of HIR with clinical prognosis and patient survival." (PMID 24571613, 2014). "Both insulin and IGF-1 have been hypothesized to play a role on cancer promotion through the Akt/PI3K/mTOR cascade that promotes cell growth and proliferation." (PMID 24267900, 2013). "Glargine, detemir and lispro, unlike regular insulin, exhibit in vitro proliferative and anti-apoptotic activities in a number of cancer cell lines." (PMID 24131755, 2013). "Taking into consideration the inhibition of insulin/IGF-I signaling pathways induced by E-cadherin expression, we went further and assessed the impact of Insulin and IGF-I signaling pathways in the modulation of bisecting GlcNAc N-glycans expression, in MDA-MB-435 cancer cells." (PMID 24282611, 2013).
cancer (continued). "Precursor polypeptide cleavage leads to the presence of two IGF1R isoforms: Isoform alpha (IGF1R-alpha), which is preferentially expressed in many cancers and is able to bind to insulin, IGF1 and IGF2, and isoform-beta (IGF1R-beta), which binds exclusively to insulin." (PMID 23365645, 2013). "Intermediate and final models with RRs (95% CIs) for insulin use (reference group: non-insulin use) for cancer events." (PMID 23308218, 2013). "The specific aim of this review, based on the most recent literature available, was to describe the effects of canola oil consumption on blood lipids, inflammation, insulin sensitivity, LDL-C oxidation, energy metabolism, and cancer compared with other dietary fat sources." (PMID 23731447, 2013). "Cancer cells expressing constitutively active phosphatidylinositol-3 kinase (PI3K) are proliferative regardless of the absence of insulin, and they form dietary restriction (DR)-resistant tumors in vivo." (PMID 23986086, 2013). "The median time under observation for cancer was longer in the non-insulin use cohort than in the insulin use cohort (50.7 months vs. 40.4 months, p<0.0001)." (PMID 23308218, 2013). "Cancer incidence rates were 78.6 and 74.3 per 10,000 patients per year in the insulin users and the non-insulin users, respectively." (PMID 23308218, 2013). "This high expression was unexpected as the majority of cancers do not derive from the principle target organs of insulin, and cancer cells have highly effective insulin-independent glucose uptake mechanisms." (PMID 23983688, 2013). "Insulin is an important growth factor for colonic mucosal cells and colonic carcinoma cells in vitro, while IGF-1 inhibits apoptosis and promotes cell cycle progression, leading to the development of cancer." (PMID 23304125, 2012). "The inverse relationship between testosterone and insulin in males without cancer has been well documented; yet the mechanisms linking these two hormonal pathways remain poorly understood." (PMID 22548055, 2012). "Hemkens et. al. found that patients treated with human insulin or insulin analogues had a higher incidence of malignant neoplasms than patients who were not treated with insulin." (PMID 22554284, 2012). "In absolute terms, approximately 44 of every 1000 patients would fall cancer for non-glargine users and the use of insulin glargine can reduce this by 1 to 14 per 1000 patients." (PMID 23284776, 2012). "Our results indicated that compared with non-galrgin insulin, insulin glargin did not increase the overall cancer incidence, but decreased the odds of overall cancer." (PMID 23284776, 2012). "Elevated insulin and IGF-1 levels are related to various cancers, such as breast and colon cancers." (PMID 22778714, 2012). "Overall, available data show that glargine has a higher mitogenic potency than human insulin in some, but not all, cancer cell lines." (PMID 23209929, 2012). "Conversely, both the UKPDS and the DIGAMI-2 study described the effects of insulin therapy on mortality from cancer, but not on the incidence of malignancies." (PMID 23209929, 2012). "The role of insulin and IGF as cancer accelerants is a relatively new idea." (PMID 23050962, 2012). "Considering what was yet unknown in the current literature on cancer cell metabolism we investigated two genes whose expression was HER2 oncogene-regulated, VAMP8 and PHGDH, for their roles in HER2 oncogene-driven insulin-independence." (PMID 21437235, 2011). "Furthermore, there is crosstalk between TGFβ signaling and the insulin/IGF-FoxO pathway in nematode longevity, mammalian stem cells, and cancer cells." (PMID 21386132, 2011). "Other signaling systems that directly affect to GLUT expression may be also altered in cancer, such as the PI3K/Akt/mTOR pathway which conveys the signal from insulin to cell." (PMID 20706540, 2010). "Glucagon, a potent insulin secretogogue, failed to augment the fasting insulin level in cachectic but did so in non-cachectic cancer patients." (PMID 698044, 1978).
cancer (continued). "Fourth, this dataset does not provide serial blood glucose, haemoglobin A1C, or insulin levels, which may affect cancer development and progression." (PMID 40507241, 2025). "Moreover, MTF's ability to modulate insulin and IGF‐1 signaling contributes to its role in metabolic regulation and may have implications for cancer prevention and treatment." (PMID 39969135, 2025). "However, exploring the effectiveness of combining therapies that potentially enhance insulin sensitivity, such as GLP‐1 agonists, GLT2 inhibitors, and exercise measures, with standard cancer treatments to improve response in specific patient groups is a promising area for future research." (PMID 39686815, 2025). "CAP modulation of INS and glucose activity in a sex-dependent manner has implications not only for understanding the ability of CAP to improve female, but not male, performance in power sports but also for the use of CAP as a adjuvant for some types of cancer therapies." (PMID 40003617, 2025). "Targeting IGF-1R individually without IR could lead to rescue mechanisms for insulin, leading to cancer advancement within unsuccessful clinical trials." (PMID 39335147, 2024). "Thus, the data suggest that insulin does not positively or negatively affect the impact of ARG on cancer cell growth." (PMID 38374190, 2024). "Insulin may also promote carcinogenesis through indirect mechanisms, via reduction in circulating levels of insulin-like growth factor (IGF)-binding proteins, leading to excess IGF-1 and IGF-2, which further promote cancer cell proliferation." (PMID 38935200, 2024). "Several cancer cells actively take up glucose in an insulin-independent manner, and the glucose taken up is not oxidatively phosphorylated in the mitochondria, which is known as the Warburg effect, but is produced by the glycolytic system for adenosine triphosphate (ATP) production." (PMID 38228757, 2024). "The top-ranked pathways included Pathways in cancer, PI3K-Akt signaling pathway, advanced glycation end products (AGE)–receptor for advanced glycation end product (RAGE) signaling pathway in diabetic complications, Insulin resistance, and Calcium signaling pathway." (PMID 39029023, 2024). "In addition, miR-27a could affect adipocyte and cancer cell metabolism by regulating its target IGF117,32,66, based on the major role of the insulin/IGF system in inhibiting apoptosis and enhancing CRC cell proliferation, differentiation, and chemoresistance." (PMID 38704452, 2024). "Some of the work addressing the relation between IGF‐1 signaling and mitochondria was conducted on cancer cell lines due to previous reports suggesting that reductions of insulin and IGF‐1 pathway signaling might turn out to be beneficial in cancer prevention and therapy." (PMID 38924381, 2024). "Additionally, it also inhibits the insulin-related down-stream signaling molecules such as NF-κB, and vascular endothelial growth factor (VEGF) to exert a pro-apoptosis and anti-angiogenesis for cancers." (PMID 38444674, 2024). "Interestingly, evidence from studies on cancers and GBM cell lines discusses the fact that metformin could disrupt the insulin signaling pathway in cancerous cells by downregulating key signaling molecules in this pathway, such as PI3K, Akt, and ERK1/2." (PMID 39267853, 2024). "Insulin is secreted into systemic circulation whereupon it binds to cell surface insulin receptors, activating intracellular PI3K signaling activity that may contribute to malignant tumor development." (PMID 38510653, 2024). "Diabetic patients present increased cancer mortality compared to those without diabetes., While cancer mortality is increased when diabetic patients are treated with insulin or sulfonylureas, it is decreased when they are treated with Metformin, which slows down tumor growth." (PMID 37601653, 2023). "Males had increased insulin sensitivity and reduced rates of cancer, but had no change in lifespan." (PMID 37881503, 2023).
cancer (continued). "Moreover, the number of new cases that required insulin was significantly higher in patients with cancer than in those without." (PMID 36831436, 2023). "A number of pathways have been proposed regarding the effect of HFPG on the incidence and progression of cancer, including via altering cell proliferation and apoptosis through impairing the regulation of inflammatory cytokines, sex hormones, insulin/insulin growth factor axis and no metabolism." (PMID 36951550, 2023). "The metabolic effects of metformin with insulin sensitizing actions result in reduction of insulin and free insulin-like growth factor (IGF-1) levels may indirectly contribute the decreased incidence of cancer." (PMID 36614197, 2023). "Although the exact mechanism for cancer genesis with high GI type of dietary pattern is not clear, but insulin resistance or insulin growth factor might be involved." (PMID 37425391, 2023). "However, plasma insulin levels are not often tested in the general population, especially in patients with cancer." (PMID 36313086, 2022). "Beneficial effects of vitamin D, such as immune-boosting, anti-inflammatory and insulin-sensitizing effects against non-cancer outcomes, may still operate after cancer diagnosis." (PMID 36014928, 2022). "However, this does not undercut the potential for insulin-targeting therapies to serve as a useful adjunct to standard-of-care therapies in cancer." (PMID 35244142, 2022). "Interestingly, insulin promotes MCF-7 breast tumor cells proliferation and migration via PI3K activation, and APN is able to downregulate the PI3K/Akt/mTOR cascade, resulting in an overall decrease in cancer cell viability, survival, and growth." (PMID 35681689, 2022). "After adjusting for confounding factors, we found that the increment of post-load plasma insulin levels from the fasting state (the post-load insulin AUC in OGTT), but not fasting plasma insulin levels, significantly associated with the increased risk of cancer." (PMID 35256755, 2022). "In all, how insulin modulates IDE expression levels or activity in cancer cells in different models, with and without the microenvironment, and how IDE inhibition in cancer cells affects the insulin/IGF pathways and, consequently, tumor metabolism and survival, are key questions worth exploring." (PMID 35406791, 2022). "Studies have also found that extremely high insulin levels in humans trigger a series of phosphorylation events that lead to the activation of multiple pathways, including the PI3K pathway, and ultimately to a highly proliferative and invasive cancer phenotype." (PMID 34034636, 2021). "Additionally, this combination has been shown to have synergistic effects in non-cancer clinical populations on outcomes relevant to cancer including body composition, aerobic fitness, fasting insulin and glucose, and IGF-1." (PMID 34629067, 2021). "Taken together, longer-term ET seems to benefit some metabolic parameters, such as lowering circulating insulin levels and elevating GLUT4 protein content in cancer patients or survivors, but it remains to be determined whether exercise elicits acute benefits for patients with cancer." (PMID 33801684, 2021). "However, based on studies involving heterogeneous human cancers (including CRC), the mechanisms of this correlation, could only be partially explained by changes in the insulin/IGF-1 axis." (PMID 34208601, 2021). "The presented data helps identify proteins affected by metformin treatment as well as insulin supplementation in EC and allows for a better understanding of the mechanism of action of the anti-cancer properties of the biguanide drug, that are still not fully understood." (PMID 33690729, 2021). "Whilst there is evidence that excess body fatness is a risk factor for aggressive PCa, it is not clear whether reducing body fatness will reduce cancer progression, and whether it does this via effects on insulin sensitivity." (PMID 34822385, 2021).
cancer (continued). "Their results suggest that surgical and metabolic response to an IA justify the adoption of an entirely laparoscopic approach performing a right colectomy for cancer, but the role of other inflammatory mediators, such as IL-1β, IL-10, IL-13, TNFα and insulin, was not considered." (PMID 33958669, 2021). "These pathways included the “transcriptional misregulation in cancer”, “pyrimidine metabolism”, “folate biosynthesis”, “MAPK signaling”, “Wnt signaling”, “phosphatidylinositol signaling system”, “T cell receptor signaling”, “axon guidance”, “insulin signaling”, and “mTOR signaling” pathways." (PMID 33627637, 2021). "In addition, we found that the viability of primary lymphocytes, isolated from peripheral blood of healthy volunteers, as well as the viability of the human cancer cells, were not affected by the presence of the INS peptide." (PMID 33958722, 2021). "Similarly, pathway analysis classified genes regulated by EGCG as being involved in steroid biosynthesis, pathways in cancer, chemokine signaling, TGF-beta signaling, cytokine-cytokine receptor interaction, MAPK signaling, IL-17 signaling, insulin secretion, FoxO signaling, and mTOR signaling." (PMID 34881283, 2021). "Furthermore, KEGG pathway analysis demonstrated that the target genes of differentially expressed miRNAs in fish liver were primarily involved in the insulin signaling pathway, PPAR signaling pathway, Wnt signaling pathway, and transcriptional misregulation in cancer." (PMID 31936480, 2020). "Here the mortality rate of all cancers was comparable between insulin and no-medication groups." (PMID 32570776, 2020). "IGF1R, one of the members of the insulin/IGF system, was mostly expressed in foetal and cancer tissues 39 and three CpG islands are predicted in the promoter region of IGF1R which may combine large list of transcript factors including MZF1, TCFL5, USF1, ETS1 and SPIB." (PMID 33085184, 2020). "Insulin, insulin-like growth factor-1 (IGF-1), and insulin-like growth factor-2 (IGF-2) are ligands for the transmembrane tyrosine kinase receptors, insulin receptor (IR), and IGF-1 receptor (IGF-1R), which have important roles in growth, development, cancer, and metabolic disease." (PMID 33604295, 2020). "Furthermore, KEGG pathway analysis demonstrated that the target genes of differentially expressed miRNAs in the liver predominantly participated in the insulin signaling pathway, PPAR signaling pathway, mRNA surveillance pathway, Wnt signaling pathway, and transcriptional dysregulation in cancer." (PMID 31936480, 2020). "This long-term cohort study may suggest a role for basal elevated insulin levels, mainly as a negative predictor in cancer prognosis." (PMID 32153503, 2020). "In addition to playing a role in the biological processes described as above, CRNDE has been reported to be regulated by insulin and insulin-like growth factors (IGFs) through the PI3K/Akt/mTOR and Raf/MAPK pathways, thereby affecting glucose metabolism and cancer microenvironment." (PMID 32435153, 2020). "For these reasons, some antidiabetic drugs like sulfonylureas, known to act by stimulating the pancreatic secretion of insulin, may have a negative impact on cancer growth." (PMID 32046158, 2020). "Third, an ever-growing number of pre-clinical studies have proposed numerous cell-autonomous (e.g., AMPK/mTOR-related) and non-cell-autonomous (e.g., insulin/IGF-1-related) molecular mechanisms that have enthusiastically endorsed the clinical development of metformin as a novel anti-cancer drug." (PMID 30984619, 2019). "Notably, resistance to the growth limiting effects of STF has been observed in cancer cells carrying mutations that cause a constitutive activation of the PI3K pathway, since these cells proliferate even in the absence of insulin or IGF-1." (PMID 31113478, 2019).